DDX5 (DEAD-box helicase 5)
Diseases named in the same sentence as DDX5 in open-access papers (continued):
Sharing a sentence is not in itself a finding about the gene and the disease.
infection (continued). "Despite the predominantly nuclear localization in uninfected cells, confocal microscopy analyses showed that DDX5 re-localizes to the cytoplasm in the presence of the virus and co-localizes with the viral genomic RNA at 24 h post infection, suggesting that DDX5 is recruited to the viral RNA." (PMID 38553727, 2024). "Moreover, DDX5 promotes infection of RNA viruses by regulating N6-methyladenosine (m6A) levels on DHX58 and nuclear factor kappa beta (NF-κB) transcripts to dampen antiviral innate immunity." (PMID 38182816, 2024). "In general, unlike other RNA viruses and DNA viruses, infection by influenza A viruses did not cause changes in the protein level and nucleocytoplasmic distribution of DDX5 in A549 cells." (PMID 35583334, 2022). "Whilst dsRNA can be found associated with DDX5 by dot blot analyses, confocal co-immunostaining analyses using the J2 antibody as a proxy for dsRNA do not demonstrate a clear co-localization of DDX5 and dsRNA upon SINV-infection, but rather indicate a proximity between the protein and dsRNA." (PMID 38553727, 2024). "Specifically, DDX5 was found to negatively modulate FMDV IRES-driven translation and suppress viral RNA replication during infection." (PMID 41615185, 2026). "That study proposed that DDX5 regulates the interaction between METTL3 with its adaptor, METTL14, after infection." (PMID 40214229, 2025). "Here, we found two host proteins, DDX5 and DDX17, that are required by KSHV and EBV for lytic reactivation, a phase of infection that is important for virus production." (PMID 40257982, 2025). "As previously reported, the protein levels of both DDX7 isoforms (p72 and p82) increased in DDX5 KO HCT116 compared to WT HCT116 cells and such an effect was independent on the infection." (PMID 38553727, 2024). "Enforced expression of CnA, NFAT1, DDX5, and other effector proteins in NFAT signaling resulted in a significant enhancement of ΔNsp1 replication, mimicking NFAT activation during natural infection." (PMID 38411085, 2024). "Compared with DDX5+/+ mice, DDX5 was expressed at a much lower level in the lungs of DDX5+/- mice, whereas the opposite was observed for TLR4 during 0–24 h post-infection with P. multocida." (PMID 38182816, 2024). "The RNA-binding activity of several proteins increased throughout the infection, such as DDX1, DDX3X, DDX5, and HNRNPA1, indicating that SARS-CoV-2 requires these proteins in the replication and transcription processes." (PMID 37314180, 2023). "After depletion of endogenous DDX5, p24 production from wild-type HIV-1NL4-3 infection was reduced by 30% and the p24 production of another type of HIV-1 clone (pNL4-3ΔEnv-GFP) was decreased by ∼72%." (PMID 23741449, 2013). "For example, DDX5 and DDX19A promote TBK1 degradation, preventing the interaction of TBK1 with IRF3 and resulting in decreased IRF3 activation and IFN production during spring viremia of carp virus (SVCV) and EMCV infection, respectively." (PMID 39620586, 2025). "Since viral gene transcription was lower upon DDX5/17 knockdown, we hypothesized that DDX5 and DDX17 are important for primary infection." (PMID 40257982, 2025). "We also find that DDX5 and DDX17 are important for primary infection of KSHV in endothelial cells." (PMID 40257982, 2025). "DDX5 and DDX17 also modulate infection of RNA viruses owing to their RNA-binding properties." (PMID 40257982, 2025). "For instance, depletion of DDX17 but not of DDX5 increases infection of Rift Valley Fever virus (RVFV), a segmented, negative-sense RNA virus." (PMID 38553727, 2024). "The interaction between DDX5 and the three viral proteins (C, NS3, and NS5) co-localized with viral RNA in the cytoplasm during infection might facilitate the unwinding the intermediate RNA duplexes." (PMID 29642538, 2018). "Hence, DDX5 and DDX17 aid in primary infection of KSHV in endothelial cells." (PMID 40257982, 2025).
infection (continued). "Furthermore, DDX5 could inhibit IFN-β and IL-6 production after infection with influenza virus, which suggests that DDX5 may be involved in regulating antiviral innate signaling." (PMID 35583334, 2022). "Infection by these nonviral pathogens is enhanced by the negative regulation of PAMP sensing and inflammatory pathways by a number of DEAD/H‐box helicases, including DDX5 and MDA5." (PMID 39620586, 2025).
bacterial infection (2 papers, 2022 to 2024). "Furthermore, DDX5 underwent K48-linked ubiquitination, which then facilitated its degradation via the proteasome during bacterial infection." (PMID 38182816, 2024). "During bacterial infection, DDX5 was recruited to and degraded by an ER-localized E3 ligase Hrd1 via the ubiquitin-proteasome pathway." (PMID 38182816, 2024). "Although our previous study found that DDX5 is involved in m6A modification during antiviral innate immunity, its roles in bacterial infection remained unclear." (PMID 38182816, 2024). "Upon bacterial infection, DDX5 is recruited to Hrd1 at the endoplasmic reticulum in an MyD88-dependent manner and is degraded by the ubiquitin-proteasome pathway." (PMID 38182816, 2024). "To determine the precise role of DDX5 during inflammation, we investigated the binding partners of DDX5 upon bacterial infection." (PMID 38182816, 2024). "Unlike DHX29 or DDX19A, which act as viral RNA sensors and activators of inflammation through the NF-κB or NLRP3 pathways, DDX5 regulates the m6A modification of TLR2/4 mRNA to suppress inflammatory responses pathway during bacterial infection." (PMID 38182816, 2024). "To evaluate the role of DDX5 during bacterial infection, we first examined the effect of DDX5 on inflammatory responses in vivo." (PMID 38182816, 2024). "Our findings show that DDX5 acts as a molecular switch to regulate inflammation during bacterial infection and shed light on mechanisms of quiescent inflammation during homeostasis." (PMID 38182816, 2024). "Conversely, following bacterial infection, DDX5 was targeted by Hrd1, an ER-localized E3 ligase, and subsequently degraded." (PMID 38182816, 2024). "In the present study, we investigated the biological functions of DDX5 during bacterial infection with a focus on its role in bacteria-promoted inflammation." (PMID 38182816, 2024). "All these results suggest that DDX5/METTL3/METTL14-mediated m6A modification suppresses the TLR2/4/NF-κB-mediated inflammatory signaling pathway in vivo during bacterial infection." (PMID 38182816, 2024). "This study not only demonstrates that DDX5 is a critical regulator of inflammation upon bacterial infection, but also highlights the molecular basis of the switch between inflammation and homeostasis." (PMID 38182816, 2024). "This is not only the first report of a pivotal role played by RNA helicases in response to bacterial infection but also exhibited the role of DDX5 in modulating inflammation quiescence during homeostasis." (PMID 38182816, 2024). "As our data demonstrated the crucial role of DDX5 in modulating inflammatory responses upon bacterial infection, we next explored how DDX5 was affected by bacterial infection or TLR agonists." (PMID 38182816, 2024). "DDX5 serves as a molecular switch to regulate inflammation during bacterial infection." (PMID 38182816, 2024). "Therefore, we employed Mettl3 cKO mice to verify the role of DDX5/METTL3-mediated m6A machinery during bacterial infection in vivo." (PMID 38182816, 2024). "Thus, our study not only sheds light on the regulatory function of DDX5 in inflammation following bacterial infection but also reveals a novel mechanism by which inflammation homeostasis is maintained." (PMID 38182816, 2024). "Because the expression of DDX5 decreased following treatment with TLR2/4 agonists in both MEFs and mouse macrophages, we hypothesized that post-translational modifications, such as phosphorylation, SUMOylation, or ubiquitination could be involved in downregulating DDX5 upon bacterial infection." (PMID 38182816, 2024). "Overall, these findings demonstrate that bacterial infection or TLR activation induce DDX5 degradation via the ubiquitin-proteasome pathway and that Hrd1 is the bona fide E3 ligase for DDX5." (PMID 38182816, 2024). "We therefore aimed to evaluate the possibility of DDX5 forming a complex with METTL3 and METTL14 during bacterial infection." (PMID 38182816, 2024).
bacterial infection (continued). "In the absence of bacterial infection, DDX5 forms a complex with METTL3 and METTL14, which regulates target transcripts, including TLR2/4 mRNAs, through m6A modification." (PMID 38182816, 2024). "We discovered that under normal conditions (i.e., without bacterial infection), DDX5 interacts with two known m6A writer proteins, METTL3 and METTL14, to form a ternary m6A writer complex, which recognizes and binds to TLR2/4 mRNAs to introduce m6A modifications." (PMID 38182816, 2024).
intestinal diseases (1 paper, 2020). "Identification of DDX5 as a common upstream regulator of tissue-specific oncogenic molecules provides an excellent therapeutic target for intestinal diseases." (PMID 32817263, 2020).
DDX5 also shares sentences with these, for which no sentence is quoted: adenoma (2 papers); Azoospermia (2); colon adenocarcinoma (2); diffuse large B-cell lymphoma (2); esophageal cancer (2); head and neck squamous cell carcinoma (2); inflammatory skin disease (2); polyp (2); adenocarcinoma (1); alveolar rhabdomyosarcoma (1); amyotrophic lateral sclerosis (1); atopic dermatitis (1); bone marrow failure (1); cataract (1); Fanconi anemia (1); hematologic malignancies (1); inflammation (1); Intellectual disability (1); liver diseases (1); lung squamous cell carcinoma (1); lymphoid neoplasm (1); melanoma (1); mental disorder (1); mesothelioma (1); metabolic disease (1); myopia (1); neurodevelopmental disorder (1); neurological disorders (1); ovarian carcinoma (1); pancreatic adenocarcinoma (1).
A further 17 diseases each share a sentence with DDX5 in 1 paper.